GFRA1 (GDNF family receptor alpha 1)
Description:
Coreceptor for GDNF, a neurotrophic factor that enhances survival and morphological differentiation of dopaminergic neurons and increases their high-affinity dopamine uptake. GDNF-binding leads to autophosphorylation and activation of the RET receptor.
Synonyms: GDNFR-alpha-1; GFR-alpha-1; GDNFRA; RETL1; TRNR1; GDNFR; RET1L; GFRalpha-1; RHDA4
Tractability: Antibody: its Gene Ontology location is reachable by antibodies, with high confidence; UniProt places it where antibodies can reach, with medium confidence; UniProt predicts a signal peptide or a membrane-spanning region. PROTAC: its protein half-life has been measured. Other modalities: a drug acting on it is in phase 2 or 3 trials.
Target class: Membrane receptor
Gene: Protein-coding gene on chromosome 10 (116,056,925 to 116,276,803, reverse strand). Ensembl gene ENSG00000151892.
Subcellular location: Cell membrane; Golgi apparatus, trans-Golgi network; Endosome; Endosome, multivesicular body
Subcellular location (Human Protein Atlas): Golgi apparatus; Nucleoplasm
Pathways (Reactome):
Developmental Biology: Formation of the ureteric bud; NCAM1 interactions; RET signaling
Signal Transduction: RAF/MAP kinase cascade
Gene Ontology:
Molecular function: glial cell-derived neurotrophic factor receptor activity; signaling receptor activity; signaling receptor binding; integrin binding; neurotrophin receptor activity
Biological process: glial cell-derived neurotrophic factor receptor signaling pathway; cell surface receptor signaling pathway; nervous system development; cell migration; cell surface receptor protein tyrosine kinase signaling pathway; kidney development; male gonad development; neuron differentiation; neuron projection development; neurotrophin signaling pathway
Cellular component: extracellular exosome; endosome; external side of plasma membrane; extrinsic component of membrane; plasma membrane; receptor complex; axon; extracellular region; Golgi apparatus; multivesicular body; neuronal cell body; plasma membrane protein complex
Genetic constraint (gnomAD): Loss-of-function variants: 10 observed, 38.12 expected, observed/expected ratio (o/e) 0.26, 90% interval 0.16 to 0.44. The upper end of that interval is the gene's LOEUF score, 0.44, which puts it in group 1 of 6, group 1 being the genes least tolerant of losing a copy. Missense variants: 450 observed, 531.16 expected, observed/expected ratio (o/e) 0.85, 90% interval 0.78 to 0.92. Synonymous variants: 238 observed, 218.09 expected, observed/expected ratio (o/e) 1.09, 90% interval 0.98 to 1.22.
Homologues: Orthologues: chimpanzee GFRA1 (100% identical), macaque GFRA1 (97% identical), guinea pig GFRA1 (96% identical), rabbit GFRA1 (95% identical), dog GFRA1 (95% identical), pig GFRA1 (94% identical), mouse Gfra1 (93% identical), rat Gfra1 (93% identical), zebrafish gfra1b (60% identical), tropical clawed frog gfra1 (55% identical), Drosophila melanogaster Gfrl (27% identical), Caenorhabditis elegans Y69A2AR.31 (25% identical), and 1 more. Paralogues in human: GFRA2 (45% identical), GFRA3 (28% identical), GFRA4 (22% identical), GFRAL (17% identical).
Diseases named in the same sentence as GFRA1 in open-access papers:
GFRA1 is named in the same sentence as 93 diseases in open-access papers, as found by Europe PMC text mining. Sharing a sentence is not in itself a finding about the gene and the disease. The quoted sentences say what the papers report.
breast carcinoma (21 papers, 2005 to 2026). "Individual transcripts with the most significant changes in AA patients included AR and GFRA1, which have been previously implicated in Pan-Gyn malignancies and breast cancer, respectively." (PMID 35992327, 2022). "Elevated GFRα1 expression in breast cancer has also been linked to lymph node metastasis and poor prognosis." (PMID 33233403, 2020). "In breast cancer patients, elevated GFRα1 expression has been linked to tumor lymph-node metastases and ultimately, the goal of oHSV targeting to GFRα1-expressing cells is therefore to enable safe and effective system-wide treatment." (PMID 33233403, 2020). "RET and GFRα1 are implicated in promoting breast cancer-cell survival, proliferation and migration and in vitro data support the involvement of RET signaling pathways in development of drug resistance." (PMID 33233403, 2020). "It has been reported that GFRA1 is overexpressed in breast cancer and positively associated with lymphovascular invasion, lymph node metastasis and advanced stages." (PMID 29037220, 2017). "Increased GFRα1 expression has been previously reported in breast cancer, and its expression is associated with tumor lymph node metastases and poor survival in patients." (PMID 25120606, 2014). "Moreover, this virus enters and spreads in GFRα1-positive breast cancer cells in vitro and caused tumor regression upon intratumoral injection in vivo." (PMID 33233403, 2020). "Moreover, both GFRα1 and GFRα3 expression were significantly associated with survival outcome of patients with mammary carcinoma by univariate and multivariate analyses, whereas expression of SDC3 was not." (PMID 23351331, 2013). "Moreover, GFRα1 expression were significantly associated with survival outcome of breast cancer." (PMID 29037220, 2017). "This virus selectively infected GFRα1-positive breast cancer cells, leading to tumor regression in vivo." (PMID 41403403, 2026). "The essential role of the GFRα family proteins in RET-mediated signal transduction has been recapitulated in breast cancer cell lines, with GFRα1 expression a limiting factor for GDNF-mediated signal activation in multiple in vitro studies." (PMID 36918928, 2023). "Abundant expression of GFRα1 was confirmed in tissues of luminal A breast cancer, which comprise 70% of breast cancer cases, while minimal or no expression was observed in normal human breast tissue." (PMID 35582425, 2022). "Early investigations of RET in breast cancer were primarily focused on estrogen receptor-alpha-positive (ER+) cases due to the prevalent co-overexpression of RET and its co-receptor, GFRα1, in a subset of ER+ breast cancers." (PMID 35957881, 2022). "A literature review indicated that the GFRα family, consisting of GFRα1-4, is involved in breast cancer, colorectal cancer, prostate cancer, lung cancer, gastric cancer, and many other tumors, thus exhibiting a diverse oncogenic portfolio." (PMID 35582425, 2022). "GDNF family receptor alpha-1 (GFRA1) has been reported to play an oncogenic role in breast cancer and pancreatic cancer." (PMID 33817274, 2020). "The receptor tyrosine kinase RET (“REarranged during Transfection”) and its coreceptors of the GDNF family, including GFRα1, are frequently upregulated in ER+ breast cancer cases." (PMID 33233403, 2020). "RET and its coreceptors therefore represent viable therapeutic targets for use in conjunction with current breast cancer therapies, and GFRα1 has recently been assessed as a target for antibody-drug conjugates." (PMID 33233403, 2020). "In cancer promotion function, GFRA1 gene can encode GFRA1 protein to promote tumor progression by activating RET and downstream pathways in breast cancer and pancreatic cancer." (PMID 33175846, 2020). "We confirmed that only the ER+ MCF7 and HCC1500 cell lines express GFRα1, raising the expectation that our GFRα1-specific oHSV will seek out a distinct subtype of breast cancer cells than the previously developed HER2-retargeted oHSVs." (PMID 33233403, 2020).
breast carcinoma (continued). "GFRα1 displays a limited expression profile in normal adult tissue, but is upregulated in a subset of breast cancers." (PMID 33233403, 2020). "While these results do not fully exclude contributions from other receptors, they are in line with the conclusion that GFRα1 expression is the key to efficient infection of breast cancer cells by KNTc-gD:GDNFΔ38." (PMID 33233403, 2020). "Here we report the design of a fully retargeted oHSV for preferential infection of breast cancer cells through virus recognition of GFRα1, the cellular receptor for glial cell-derived neurotrophic factor (GDNF)." (PMID 33233403, 2020). "For illustration, circ-GFRA1 sponges miR-34a and promotes the progression of breast cancer by modulating GFRA1." (PMID 31911754, 2020). "In summary, our work has demonstrated that GFRA1 can serve as a TAA in multiple subsets of breast cancer." (PMID 29796165, 2018). "Antibody-drug conjugates targeted to RET or GFRα1, have demonstrated effective and specific killing of breast cancer cells in vitro and in vivo." (PMID 30666215, 2018). "Using an unbiased genomics approach to uncover membrane-localized tumor-associated antigens (TAAs), we have identified glial cell line derived neurotrophic factor (GDNF) family receptor α 1 (GFRA1) as a breast cancer TAA." (PMID 29796165, 2018). "Immunohistochemistry (IHC) revealed that GFRA1 displays a limited normal tissue expression profile coupled with overexpression in specific breast cancer subsets." (PMID 29796165, 2018). "To date, only the RET-ADCs Y078- DM1 and Y078-DM4 have been described as targeting a similar pathway to GFRA1-mediated inhibition in breast cancer." (PMID 29796165, 2018). "In an assay of serum samples from healthy donors and patients with ER-positive breast cancer or TNBC, the level of soluble GFRA1 was similarly low between serum from patients with breast cancer and that from healthy donors." (PMID 29796165, 2018). "IHC staining patterns on multi-tumor and disease-specific tumor microarrays revealed GFRA1 expression in all breast cancer subsets." (PMID 29796165, 2018). "The GFRA1 axis is reported to promote breast cancer proliferation and invasion, and its expression correlates with lymph node metastases and advanced clinical stage." (PMID 29796165, 2018). "Further analysis of the mRNA-seq data set found that GFRA1 is also strongly correlated with ESR1 mRNA in breast cancers (Spearman’s ρ = 0.52, p < 2.2e-16), suggesting that it is also a direct target of E2 signaling." (PMID 29608602, 2018). "Since both RET and GFRA1 are naturally high in ER+ breast cancer cells, and since high expression of these factors appears to be established in part by ERα, there must be other causes of endocrine resistance, both in cell models and in vivo." (PMID 29608602, 2018). "cDNA array gene expression profiling of a normal human cDNA array and two different breast cancer arrays confirmed the significant overexpression of GFRA1 in breast cancers and limited expression in normal tissues." (PMID 29796165, 2018). "It is also up-regulated in breast carcinoma while GFRA1 released by cells can promote cancer cell migration and invasion." (PMID 27144453, 2016). "GFRα1 expression is upregulated in a significant proportion of human breast cancers 29-31." (PMID 35582425, 2022). "On the one hand, GFRα1 was identified as a target protein of ST3 beta-galactoside alpha-2,3-sialyltransferase 1 (ST3GAL1), which regulates the GDNF/GFRα1/RET pathway in breast cancer cells by mediating O-linked sialylation of GFRα1 and facilitating its interaction with RET." (PMID 35582425, 2022). "In addition, GFRA1 can promote the proliferation and migration in pancreatic cancer and breast cancer, and induce chemotherapy resistance in osteosarcoma." (PMID 33175846, 2020).
breast carcinoma (continued). "In particular, GFRα1 expression was upregulated compared to normal breast tissue in almost 60% of breast cancer patients sampled and this upregulation was correlated with estrogen receptor (ER)-positive breast cancer cases." (PMID 33233403, 2020). "Furthermore, GFRA1 gene can also guide the generation of circRNA to regulate microRNA as an oncogene in breast cancer and ovarian cancer." (PMID 33175846, 2020). "GFRA1, a cancer-promoting gene in pancreatic and breast cancers, was selected for further analysis." (PMID 33175846, 2020). "First, GFRA1 overexpression is nearly twice as prevalent as RET, as was shown by a detailed IHC analysis in 245 breast cancers; thus, targeting GFRA1 could reach a wider range of breast cancers." (PMID 29796165, 2018). "RET and GFRα1 are expressed in approximately 30–70% of human breast cancers." (PMID 30666215, 2018). "Indeed, we find that expression of RET and GFRα1 are both highest in ER+ breast cancers, likely because of direct transcriptional activation of both genes by E2/ ERα." (PMID 29608602, 2018). "In contrast, GFRA1 is overexpressed in the majority of breast cancers." (PMID 29796165, 2018). "We also found evidence that ERα may itself play an important role in establishing expression of the RET receptor and its GFRA1 co-receptor in breast cancer cells." (PMID 29608602, 2018). "Although the shed antigen sink cannot be detected in breast cancer patient sera, it could be a challenge facing development of an effective GFRA1-targeted therapeutic and should be further analyzed." (PMID 29796165, 2018). "To explore whether circGFRA1 acts as a ceRNA to sequester miR-34a and liberate the expression of GFRA1, we continued to detect the expression of GFRA1 in breast cancer cell lines and tissues." (PMID 29037220, 2017). "In addition, the stimulation of GFRα1-positive breast cancer cells with GDNF has been previously demonstrated to enhance cell proliferation and survival in vivo." (PMID 25120606, 2014). "Thus, our findings uncover two breast cancer subsets that lack adequate treatment options and could respond to a GFRA1-targeted ADC." (PMID 29796165, 2018). "Furthermore, GFRA1 is more prevalent and highly expressed in tumors that have become refractory to chemotherapeutics, and expression of this signaling pathway can facilitate resistance to aromatase inhibitors used in breast cancer therapy." (PMID 29796165, 2018). "Thus, GFRA1 could serve as a TAA for ADC targeting in breast cancers that require alternative therapeutic strategies." (PMID 29796165, 2018). "For breast cancer, KNTc-gD:GDNF retargeted GFRα1 by replacing the gD signal peptide and HVEM-binding domain with pre-pro-GDNF and deleting aa 38 to prevent nectin-1 binding." (PMID 41403403, 2026). "Using a combination of these markers, 60 HR+/HER2+ breast cancer patients were classified into the following subtypes: (a) IHC-III: CD8A+; (b) IHC-IV: CD8A− and KRT5+; (c) IHC-II: CD8A−, KRT5− and GFRA1+; (d) IHC-I: CD8A−, KRT5−, GFRA1− and PFKP+." (PMID 40133264, 2025). "ER is a central transcription factor in breast cancer, inducing both RET and GFRA1 gene expression, which reciprocally function to enhance estrogen-driven cell proliferation." (PMID 36918928, 2023). "We chose four human breast cancer lines, MCF7, HCC1500, MDA-MB-453, and MDA-MB-231, and assessed GFRα1 expression by Western blot." (PMID 33233403, 2020). "Thus, GFRA1 may be useful predictors of disease progression and outcome of breast cancers." (PMID 29037220, 2017). "Concerning the candidate genes identified as potential molecular biomarkers for rectal cancer, GFRA1, and GSTM2, aberrant methylation of GSTM2 has previously been identified in prostate cancer, breast cancer and oral squamous cell carcinoma." (PMID 27566576, 2016).
breast carcinoma (continued). "We determined the mRNA and protein expression of three proteins demonstrated to bind ARTN, namely GFRα1, GFRα3 and Syndecan-3 (SDC3), in benign breast disease and mammary carcinoma by in situ hybridization and immunohistochemistry, respectively." (PMID 23351331, 2013). "In these cell lines, it has been consistently demonstrated that treatment with estradiol (E2) induces transcription of multiple RET signaling system components, including RET, GFRA1, and ARTN, suggesting a regulatory mechanism for RET’s functions in breast cancer." (PMID 36918928, 2023). "The GFRα1-targeted vector efficiently transduced and killed human breast cancer cells bearing the receptor, while cells not expressing the receptor remained uninfected, even at high multiplicity of infection (MOI)." (PMID 33233403, 2020). "GFRA1 was also expressed highly in breast cancer tissue, while other tumor types did not exhibit significant expression." (PMID 29796165, 2018). "Moreover, we also show that mRNA abundance of both RET and GFRA1 correlate with ESR1 across primary breast cancers, suggesting that RET and GFRA1 are direct targets of ERα signaling in primary patients as well." (PMID 29608602, 2018). "By a comparison of RNA-seq data in primary breast cancers, we show that both RET and GFRA1 correlate with expression of ESR1, suggesting that they may be targets of ERα signaling in primary tumors." (PMID 29608602, 2018). "The expression of GFRα1 and GFRα3, but not SDC3, was significantly increased in mammary carcinoma and positively associated with tumor lymph node metastases, higher clinical stage and HER-2 positivity." (PMID 23351331, 2013). "The expression of GFRα1 and/or GFRα3, especially when combined with ARTN expression, may be useful predictors of disease progression and outcome in specific subtypes of mammary carcinoma." (PMID 23351331, 2013). "Indeed, we demonstrated that the retargeted virus efficiently infected and killed GFRα1-positive, but not GFRα1-negative, breast cancer cells in vitro, and knockdown of GFRα1 protein expression significantly reduced retargeted virus infection." (PMID 33233403, 2020). "Furthermore, significant association of GFRα1 and GFRα3 expression with survival outcome observed herein were restricted to ER negative or HER-2 negative mammary carcinoma." (PMID 23351331, 2013). "Co-expression of ARTN with either GFRα1 or GFRα3, but not SDC3, produced synergistic increases in the odds ratio for both relapse-free and overall survival in patients with mammary carcinoma." (PMID 23351331, 2013).
triple-negative breast carcinoma (11 papers, 2017 to 2021). An invasive breast carcinoma which is negative for expression of estrogen receptor (ER), progesterone receptor (PR), and human epidermal growth factor receptor 2 (HER2). "For instance, circGFRA1 functions as the ceRNA of GFRA1 by regulating miR-34a in triple negative breast cancer." (PMID 32493490, 2020). "Both circGFRA1 and GFRA1 are upregulated in triple negative breast cancer (TNBC), and circGFRA1 functions as a ceRNA to regulate GFRA1 expression by decoying miR-34a." (PMID 30111313, 2018). "CircRNAs as ceRNAs regulate the expression of GDNF family receptor alpha-1 (GFRA1) by regulating the levels of miR-34a, and they have an anti-apoptotic function in triple-negative breast cancer." (PMID 29626935, 2018). "Another research group found that circular GFRA1 RNA (circGFRA1) regulates GFRA1 expression through sponging miR-34a to exert regulatory functions in triple negative breast cancer (TNBC)." (PMID 29617307, 2018). "In triple-negative breast cancer, circGFRA1 acts as miR-34a ceRNA to regulate GFRA1 expression, while circEPSTI1 promotes triple-negative breast cancer cell proliferation through a novel pathway by sponging miR-4753 and miR-6809 and upregulating the oncogene BCL11A." (PMID 30626395, 2019). "CircRNAs circGFRA1 and GFRA1 act as ceRNAs in triple negative breast cancer by regulating miR-34a." (PMID 30598076, 2018). "It has been shown that circRNAs act as ceRNAs to regulate GDNF family receptor alpha-1 (GFRA1) expression via modulating miR-34a levels, thus exerting anti-apoptotic functions in triple-negative breast cancer." (PMID 34771517, 2021).